CCL22 (C-C motif chemokine ligand 22)
Diseases named in the same sentence as CCL22 in open-access papers (continued):
Sharing a sentence is not in itself a finding about the gene and the disease.
ischemic stroke (3 papers, 2019 to 2024). A stroke disorder caused by obstruction of blood flow to the brain, due to thrombotic (local blood clot formation) or embolic (due to a blood clot or other material traveling from another site) event. "Previously, we identified the human orthologues for a number of rat genes, which expression was changed after ischaemic stroke (Adora2a, Bcl3, Ccl22, Ccr1, Cd14, Gpr6, Gpr88, Rgs9, and other genes)." (PMID 34946819, 2021). "CCL22 is mainly produced by macrophages and DCs33, 34; reduction of CCL22 in the lungs indicates a possible functional impairment of these cells following ischemic stroke, which warrants further investigation." (PMID 31691533, 2019).
leprosy (3 papers, 2013 to 2025). Leprosy is a chronic infectious disease affecting primarily the skin and peripheral nervous system. "CCR4 serves as the receptor for CCL17 and CCL22, the latter displaying the most prominent difference in this study between contacts and patients with leprosy, with unprecedented discriminatory potential for BT/TT patients and contacts." (PMID 40683203, 2025). "Both types of reactions are associated with significant increase of Th17 cells and associated cytokines IL-17A, IL-17F, IL-21, IL-23 and chemokines CCL20, CCL22 as compared to matching stable forms of leprosy." (PMID 27035913, 2016). "Expression of MMP3, MMP13, CCL22 were seen to be highest in PBMC cultures of healthy contacts as compared to leprosy types." (PMID 23936569, 2013). "The high levels of CCL22 observed in contacts compared to patients suggest better control of T cell immunity against M. leprae, avoiding excessive (auto)immunity as is the case in the tuberculoid part (BT/TT) of the leprosy disease spectrum." (PMID 40683203, 2025). "CCL22 showed decrease in LL as compared to healthy subjects (p<0.01) but did not discriminate the leprosy types." (PMID 23936569, 2013).
malaria (3 papers, 2014 to 2025). Malaria is a serious and sometimes fatal disease caused by a parasite that commonly infects a certain type of mosquito which feeds on humans. "There were marked elevations of both M1 and M2 factors noted in SM and CM, and low levels of the M2-related chemokines in CCL17 and CCL22 in children with malaria." (PMID 27385484, 2016). "The precise meaning of the lower levels of CCL17 and CCL22 in malaria is currently unknown, but it does underscore the complexity of simply analyzing plasma chemokines as markers of mononuclear phagocyte activation status." (PMID 27385484, 2016). "Notably of the chemokines and cytokines we measured, CCL17 [“thymus and activation related chemokine” (TARC)] and CCL22 [“macrophage derived chemokine” (MDC)] are the only two that are low in malaria." (PMID 27385484, 2016).
neuropathy (3 papers, 2020 to 2023). A disorder affecting the nervous system that manifests with pain, tingling, numbness, and/or muscle weakness. "Our biochemical studies were performed in rats exposed to CCI and revealed increased levels of CCL17 and CCL22 in the dorsal root ganglia during the development of neuropathy." (PMID 36555280, 2022). "Moreover, taking into consideration our results and aforesaid literature, all three chemokines acting via CCR4, that is, CCL17, CCL22, and CCL2, seem to be important mediators in pathological nociceptive processes at the DRG level under neuropathy." (PMID 32760393, 2020). "However, the levels of CCL17 and CCL22 in the spinal cords of rats and mice in this model were not changed in the early and late stages of neuropathy." (PMID 36555280, 2022).
non-small cell lung carcinoma (3 papers, 2022 to 2023). A group of at least three distinct histological types of lung cancer, including non-small cell squamous cell carcinoma, adenocarcinoma, and large cell carcinoma. "The RT-qPCR results showed that, the expression of LncRNA HOTAIR was up-regulated, while the expression of CCL22 mRNA was down-regulated in the non-small cell lung cancer clinical samples compared with adjacent normal tissues." (PMID 35176085, 2022).
preeclampsia (3 papers, 2021 to 2025). Preeclampsia is a hypertensive disorder of pregnancy that is characterized by new-onset hypertension with proteinuria presenting after 20 weeks of gestation, and depending on mild or severe forms may initially present with severe headache, visual disturbances, and hyperreflexia. "Further CCL22 was revealed as a marker for preeclampsia in one study where the serum of pregnant women was analyzed." (PMID 35163802, 2022). "Using a diagnostic test assessment characteristic parameters (IL-22, MDC/CCL22, IL-2/IL-4 ratio) have been identified and cut-off values have been proposed to diagnose preeclampsia." (PMID 34248946, 2021). "Regardless of the discrepancies, the analysis of a broad panel of 53 mediators suggests that IL-22, CCL22, and the IL-2/IL-4 ratio may aid in the diagnosis of PE and even in differentiating preeclampsia from gestational hypertension." (PMID 41156157, 2025). "Generally, the role of CCL22 during pregnancy is not completely resolved and CCL22 expression in the placental tissue has not been previously investigated during preeclampsia." (PMID 35163802, 2022).
schizophrenia (3 papers, 2015 to 2024). A major psychotic disorder characterized by abnormalities in the perception or expression of reality. "Previous studies have found that serum level of CCL22 is elevated in chronic schizophrenia, predicts relapse in schizophrenia, and differentiates schizophrenia from major depressive disorder." (PMID 25970596, 2015). "In chronic bipolar patients, decreased CCL22 mRNA expression in lymphocytes has been found in comparison to patients with chronic schizophrenia." (PMID 25970596, 2015). "Furthermore, elevated CCL22 levels predicted relapse in schizophrenia patients." (PMID 32179746, 2020). "Among the 13 chemokines studied, a 7 week treatment with OLZ resulted in an increase in two homeostatic chemokines, BCL (CXCL13) and MDC (CCL22), and two inflammatory ones, KC (CXCL1) and TARC (CCL17), all of which were shown to take part in schizophrenia and other mental diseases." (PMID 39457671, 2024).
Stroke (3 papers, 2017 to 2024). Sudden impairment of blood flow to a part of the brain due to occlusion or rupture of an artery to the brain. "In particular, microglia exhibited a dominant neuroprotective M2-like response (phagocytosis and tissue repair) for the first seven days post stroke, characterized by increased expression levels of CCL22, IL10, CD206, arginase-1 and TFG-β." (PMID 34194419, 2021).
airway hyperresponsiveness (2 papers, 2020 to 2025). "Neutralizing either CCL22 or CCL17 has been shown to abrogate lung eosinophilia and airway hyperresponsiveness." (PMID 32586381, 2020).
bladder cancer (2 papers, 2015 to 2024). "We observed that BCG-induced inflammation in human bladder cancer tissues involves the induction of COX2 and its product PGE2, associated with the EP4-mediated induction of the chemokines CCL22 and CXCL8, which attract myeloid-derived suppressor cells (MDSCs) and regulatory T cells (Tregs)." (PMID 38667314, 2024). "Bladder cancer tissues spontaneously expressed high levels of the granulocyte/MDSC-attractant CXCL8 and Treg-attractant CCL22, but only marginal levels of the CTL-attracting chemokines: CCL5, CXCL9 and CXCL10." (PMID 25806105, 2015). "Unexpectedly, we observed that, while BCG strongly up regulated the secretion of CXCL8 (P < 0.05) and CCL22 (P < 0.05) by ex vivo-treated bladder cancer explants (n = 11 patients), it did not enhance CXCL10 secretion." (PMID 25806105, 2015). "Interestingly, untreated bladder cancer TMEs showed nearly a complete lack of effector cell-attracting chemokines but selective expression of Treg/MDSC attractants IL-8/CXCL8, CXCL-12, and CCL22." (PMID 38667314, 2024).
bladder tumor (2 papers, 2015 to 2021). "The prevalence of high CCL22 and CXCL8 in bladder tumors at baseline is consistent with previous studies which showed the abundance of these undesirable chemokines, particularly in patients with poor prognosis." (PMID 25806105, 2015).
brain tumor (2 papers, 2017). "Beta-Catenin facilitates growth of brain tumor initiating cells and CCL22, secreted by the tumor, recruits immunosuppressive regulatory T cells." (PMID 28594935, 2017). "Interestingly, CCL22 (C-C motif chemokine ligand 22), one of the three ceRNAs we found to jointly predict survival, is a crucial mediator of Treg migration towards brain tumors and specifically expressed in GBM (not in low-grade tumors)." (PMID 28241741, 2017).
colon adenocarcinoma (2 papers, 2022 to 2025). "The upregulation of CCL22 was accompanied by an increase in immune score and a decrease in stromal score in patients of The Cancer Genome Atlas (TCGA) colon adenocarcinoma (COAD)." (PMID 35295948, 2022).
diabetic retinopathy (2 papers, 2009 to 2022). "Similar to Ccl22, IL-12 was elevated in animal models of retinal degeneration, including light toxicity and diabetic retinopathy." (PMID 36064575, 2022).
eczema (2 papers, 2018 to 2024). "These cytokines, along with chemokines like CCL17 and CCL22, play a crucial role in recruiting and activating eosinophils and other immune cells, leading to the chronic inflammation and itchiness typical of eczema." (PMID 39670074, 2024).
encephalitis (2 papers, 2015 to 2020). An acute inflammatory process affecting the brain parenchyma. "IL-2, CXCL10, CCL3, IL-10, CCL22, and IL-6 may represent new biomarkers in patients with anti-NMDAR encephalitis." (PMID 33408682, 2020).
HIV-1 infection (2 papers, 2017 to 2019). The type species of lentivirus and the etiologic agent of acquired immunodeficiency syndrome (AIDS). "Presented data shows that the chemokines, CCL17, CCL18, and CCL22 are increased during HIV-1 infection." (PMID 30979916, 2019). "Notably, plasma levels of the TH2 chemokines CCL17 and CCL22 are also elevated during HIV-1 infection." (PMID 30979916, 2019).
inflammatory bowel disease (2 papers, 2022 to 2025). A spectrum of small and large bowel inflammatory diseases of unknown etiology. "The enriched KEGG pathways were as follows: “cytokine–cytokine receptor interaction”, “chemokine signaling pathway”, “intestinal immune network for IgA production”, and “inflammatory bowel disease”, indicating the potential role of CCL22 in gastrointestinal diseases." (PMID 35295948, 2022).
invasive breast carcinoma (2 papers, 2013 to 2018). A carcinoma that infiltrates the breast parenchyma. "We therefore aimed at analyzing the roles of the chemokines CCL1 and CCL22 in human invasive breast cancer." (PMID 30572845, 2018). "The present study was designed to assess the association of CCL22 and TGF-β1 expression in tumor cells with the status of Treg infiltration in invasive breast carcinoma, and in addition, to evaluate their prognostic significance for BC patients." (PMID 24124553, 2013). "One hundred ninety-nine tissue samples of patients with invasive breast cancer were stained for CCL1 and CCL22 by immunohistochemistry." (PMID 30572845, 2018).
migraine (2 papers, 2019 to 2021). "Levels of IL-1β, CCL3, CCL4, CXCL1, CCL22, and CCL8 were also measured in 55 healthy controls and 64 migraine patients." (PMID 34575163, 2021). "The levels of CCL18, CCL22, and CCL4 were different between patients with MD or migraine and controls." (PMID 34575163, 2021). "Therefore, a comparison between VM patients and migraine patients, namely IL- 1β, CCL3, CCL22, and CXCL1 levels, could be beneficial to understand if there is a shared cytokine profile between migraine and VM or if this cytokine signature is specific to VM." (PMID 31214186, 2019). "Therefore, we measured the levels of IL-1β, CCL3, CCL4, CXCL1, CCL22, and CCL18 in a cohort of 83 patients with MD, which included 44 EOMD and 39 LOMD, and 64 patients with migraine without vestibular symptoms to control the effect of migraine itself on cytokine levels." (PMID 34575163, 2021).
myocardial infarction (2 papers, 2022 to 2025). Gross necrosis of the myocardium, as a result of interruption of the blood supply to the area, as in coronary thrombosis. "An interesting study found that CCL17 and CCL22 can participate in the regulation of Treg chemotaxis as competitive biased ligands of CCR4 in myocardial infarction." (PMID 41266856, 2025). "CCL22 is involved in CCR4-mediated cardiac cell migration and CCL22/CCR4 polymorphisms have been associated to patients diagnosed with myocardial infarction." (PMID 35784739, 2022).
osteosarcoma (2 papers, 2023 to 2024). A usually aggressive malignant bone-forming mesenchymal neoplasm, predominantly affecting adolescents and young adults. "This study provides the clinical insight that chemokine signaling pathway genes (CCL21, CCL22, CCL24, CXCL11, CXCL12, CXCL13, GNAI2, and RAC2) in proliferating cells might be the potential biomarkers for treatment of osteosarcoma." (PMID 37537613, 2023).
radiation pneumonitis (2 papers, 2009 to 2025). Inflammation of the lung due to harmful effects of ionizing or non-ionizing radiation. "Anti-CCL22 provides a mild protective effect against radiation pneumonitis." (PMID 39808500, 2025). "There is selective upregulation of CCL22 in a rat model of radiation pneumonitis." (PMID 39808500, 2025). "In our previous study, we showed that the production of CCL22 and CCL17 in rat radiation pneumonitis increased significantly, but CCL17 was undetectable in BAL fluid of IPF patients." (PMID 19715610, 2009).
Sjögren's Syndrome (2 papers, 2018 to 2021). "Furthermore, a report demonstrating the presence of the chemokine CCL22 in both HCMV infection and Sjögren’s syndrome could potentially indicate a role for the CCR4-CCL22 axis." (PMID 34959486, 2021).
systemic sclerosis (2 papers, 2020 to 2023). A chronic disorder, possibly autoimmune, marked by excessive production of collagen which results in hardening and thickening of body tissues. "For example, the expression of CCL22, an important gene involved in systemic sclerosis, dramatically increased during the differentiation of CXCL4-moDCs." (PMID 33042127, 2020).
acute disseminated encephalomyelitis (1 paper, 2022). Acute disseminated encephalomyelitis (ADEM) is a demyelinating disorder of the central nervous system. "Unlike MS, elevated neutrophil chemokines (CXCL7) and Th2 cell chemokines (CCL1, CCL22, and CCL17) were also found in the CSF of acute disseminated encephalomyelitis (ADEM), another inflammatory demyelinating disease, helping to differentiate ADEM from MS." (PMID 35837284, 2022).
Aden (1 paper, 2021). "CCL17 and CCL22 within tumors are known to be associated with an increased population of Foxp3+ Tregs; thus, the high expression of these 2 chemokines may contribute to the infiltration of Tregs into patients with Aden, thereby making the tumor microenvironment more immune suppressive." (PMID 34459571, 2021).
anaphylaxis (1 paper, 2022). An acute hypersensitivity reaction that occurs from exposure to an allergen. "In addition, the selective elevation of IL-6 and a small panel of chemokines (CCL5, CCL20, CCL22, and CXCL1) in the spleen upon oral allergen but not saline challenge suggests their key role in eliciting anaphylaxis via the oral route." (PMID 36238931, 2022).
Anxiety (1 paper, 2012). Intense feelings of nervousness, tension, or panic often arise in response to interpersonal stresses. "Since overall biological function is ultimately influenced by relative proportions of counteracting factors, we also examined the effects of anxiety phenotype on the ratios of protective versus harmful chemokines (CTACK/CCL22) and cytokines ((IL-12+IFN-γ)/(IL-10 + IL-4))." (PMID 22558071, 2012).
apical periodontitis (1 paper, 2021). "In apical periodontitis, studies have shown that CCL22 combined with CCR4 seems to be able to recruit more Treg cells into periapical lesions of mice." (PMID 34177907, 2021). "Besides, it has been reported that LPS promotes the secretion of CCL22 in macrophages by downregulating the expression of miR-34a in the apical periodontitis model of rats." (PMID 34177907, 2021).
Atherosclerotic lesion (1 paper, 2025). A lesion associated with atherosclerosis, a multifactorial and multipart progressive disease manifested by the focal development within the arterial wall of lesions, that ranges from the development of a fatty streak, plaque progression, and plaque disruption. "Our data show that interactions between CCR4 and CCL17/CCL22 may promote Treg-skewed responses in lymphoid tissues and atherosclerotic lesions." (PMID 40608058, 2025).
autoimmune encephalitis (1 paper, 2022). Inflammation of the brain secondary to an immune response triggered by the body itself. "An increase in CCL22 and CCR4 expression was demonstrated in the central nervous system in mice that develop chronic recurrent forms of autoimmune encephalitis, which demonstrates the involvement of CCL17/CCL22/CCR4 in the pathogenesis of this disease." (PMID 36555280, 2022).
benign ovarian tumors (1 paper, 2015). "We found concentrations of CCL22 in the peritoneal fluid to be significantly elevated in women with EOC, as compared to benign ovarian tumor patients." (PMID 25647263, 2015). "However, no CCL22 concentration in the PF of women with benign ovarian tumors was assessed." (PMID 25647263, 2015).
Brain atrophy (1 paper, 2021). Partial or complete wasting (loss) of brain tissue that was once present. "The CHI3L1 (chitinase-3-like protein 1) level in the CSF was strongly correlated with brain atrophy, and the CSF levels of CXCL1, MMP-9, CCL22, CXCL13, and CXCL10 were correlated with the development of new lesions in T2 MRI." (PMID 34602928, 2021).
cervical dysplasia (1 paper, 2025). "CCL22 is a chemoattractant for a range of immune cells, including T-regs, and there is a positive correlation between CCL22 positive cells and FoxP3 positive cells in cervical dysplasia tissues." (PMID 40430784, 2025).
chronic asthma (1 paper, 2018). An asthma that is characterized by the development of persistent airway inflammation and recurrent attacks of breathlessness and wheezing, which vary in severity and frequency. "Nevertheless, our data demonstrated a previously unappreciated mechanism that in response to allergen challenge, lung cDC1s attract eosinophils directly through secreting CCL17 and CCL22 during the memory stage in chronic asthma." (PMID 30250029, 2018).
chronic lung disease (1 paper, 2021). According to the definitions of the American and British Thoracic Societies, including pulmonary functional tests, X-rays, and CT scans for items such as fibrosis, bronchiectasis, bullae, emphysema, nodular or lymphomatous abnormalities. "We analyzed the expression of selected genes associated with AM plasticity (Ccl22, Ccl17, Mmp12, and Arg1) and inflammation in chronic lung diseases (Il1a and Il1b)." (PMID 34764283, 2021).
crescentic glomerulonephritis (1 paper, 2020). A histopathologic term for a pattern of diseases characterized by extensive crescent formation in the glomeruli; patients present clinically with rapid deterioration of renal function, and possible progression to end-stage renal failure within weeks or months. "Our study has revealed a new remission mechanism whereby effector Tregs migrate into the crescentic glomerulonephritis via the CCL22/17–CCR4 axis that is facilitated by M2‐like type macrophages that are induced by IL‐6R blockade." (PMID 33163184, 2020).
cryptococcosis (1 paper, 2024). An acute or chronic, localized or disseminated infection by Cryptococcus neoformans. "The authors first used single-cell RNA sequencing to identify that Batf3-dependent cDC1 exhibited a unique mRNA signature during murine cryptococcosis, strongly upregulating transcripts related to T cell recruitment and Th1 polarization, such as Il12b, Stat4, and Ccl22." (PMID 39254303, 2024).